IL10 (interleukin 10)
Diseases named in the same sentence as IL10 in open-access papers (continued):
Sharing a sentence is not in itself a finding about the gene and the disease.
tumor (continued). "While some tumor-infiltrating B-cells promote metastasis with co-expression of PD-L1 and IL-10, others—particularly granzyme-B-producing B-cells—may boost post-chemotherapy immune responses." (PMID 40260236, 2025). "Interestingly, the anti-inflammatory cytokine IL-10 also enhanced anti-tumor effects when expressed by oncolytic VACV in a mouse model of pancreatic cancer." (PMID 40723208, 2025). "ICIs may disrupt this axis by inhibiting PD-1-mediated IL-10 upregulation, thereby modulating the tumor immunosuppressive milieu." (PMID 40821802, 2025). "Moreover, IL-10 reduced viral clearance and tumor recurrence, confirming the potential of VVLΔTK-IL-10." (PMID 40469178, 2025). "Previous evidence reveals that circulating monocytes are chemoattracted to tumor cells and differentiated into TAMs by several stimuli including IL-6, IL-10, VEGF, macrophage colony stimulating factor (M-CSF, also known as CSF-1), TGF-β, GM-CSF, and chemokines." (PMID 40050933, 2025). "These IL-10-producing γδT cells contribute to immune suppression and tumor immune evasion, raising concerns that γδT cell therapies, if not properly controlled, could inadvertently promote tumor progression." (PMID 40226616, 2025). "Moreover, these strains have also been shown to enhance the expression of antimicrobial peptides like human β-defensin (hBD) and anti-inflammatory cytokines such as IL-10, suggesting a dual role in both direct tumor suppression and immune modulation." (PMID 41305617, 2025). "The M2c phenotype, which secretes IL-10, fosters tumor evasion and metastasis." (PMID 39827422, 2025). "These molecules were demonstrated to modulate the production of pro-inflammatory cytokines, decreasing TNF-α and IL-1β release and increasing anti-inflammatory cytokine interleukin-10 (IL-10) by mouse peritoneal cells, lyse human tumor-derived cells, and mouse erythrocytes." (PMID 41003528, 2025). "Tregs suppress anti-tumor immune responses by inhibiting the activity of effector T cells and natural killer (NK) cells through the secretion of immunosuppressive cytokines such as interleukin-10 (IL-10) and transforming growth factor-beta (TGF-β)." (PMID 40427514, 2025). "The TME, enriched in M2-like tumor-associated macrophages (TAMs), regulatory T cells (Tregs), and myeloid-derived suppressor cells (MDSCs), releases suppressive cytokines (TGF-β, IL-10) and depletes essential nutrients (arginine, tryptophan), collectively impairing CAR-T function." (PMID 41383602, 2025). "Additionally, CD36+ TAMs exhibit elevated levels of interleukin-10 (IL-10) and growth factors, indicative of their anti-inflammatory phenotype and potential role in promoting tumor progression." (PMID 41341850, 2025). "Beyond direct effects on tumor cells and T cells, M2 TAMs contribute to a broader immunosuppressive environment by secreting cytokines (IL-10, TGF-β) that inhibit dendritic cell maturation, promote Treg differentiation and function, and recruit additional immunosuppressive cells like MDSCs." (PMID 40746533, 2025). "Initially identified as a potent anti-inflammatory cytokine, IL-10 has since emerged as a pleiotropic molecule with diverse regulatory roles in immune responses and cancer biology, encompassing both tumor-promoting and anti-tumor effects." (PMID 40149345, 2025). "Furthermore, IgG1 plasma cells were shown to promote the secretion of key inflammatory cytokines, including TNF-α, IL-6, and IL-10, which not only sustain immune responses but also contribute to immune evasion and tumor progression." (PMID 41357192, 2025). "Elevated levels of pro-inflammatory cytokines such as interleukin-6 (IL-6) and tumor necrosis factor-alpha (TNF-α) promote survival pathways, chemoresistance, and immune evasion, while anti-inflammatory cytokines like IL-10 further suppress effective anti-tumor immunity." (PMID 40486628, 2025).
tumor (continued). "We hypothesized that LPA-induced IL-10 production contributes to altered expression of HLA antigens, thus modulating the anti-tumor immune response." (PMID 39187677, 2025). "On the other hand, M2 macrophages arise in response to cytokines such as interleukin (IL)-4, IL-10, IL-13, and transforming growth factor-β (TGF-β), thereby restraining antitumor immunity, promoting tumor-associated vasculature formation, and advancing disease progression." (PMID 40092996, 2025). "Clinically, TAM-targeted therapies could complement existing treatments, with biomarkers like CD163 and IL-10 guiding personalized interventions, ultimately improving tumor control and patient outcomes through optimized multimodal strategies." (PMID 40264780, 2025). "Therefore, the MMW-induced alteration in the cytokine secretion profile (increased IL-12/TNF-α and decreased IL-10) likely contributes to the enhancement of macrophage anti-tumor function." (PMID 41383334, 2025). "Additionally, anti‐angiogenic therapy has been found to normalize disorganized tumor blood vessels and reduce the recruitment of immune‐inhibitory factors such as IL‐6, IL‐10, and indoleamine 2,3‐dioxygenase (IDO), improving the efficacy of immunotherapy." (PMID 40105370, 2025). "IgG4 reduces the expression of CD206, CD163, and CD14 on the surface of M2 macrophages, increases the production of CCL-1, IL-10, and IL-6, induces the M2b-like macrophage phenotype, which impairs the tumor cell phagocytosis function and the function of anti-cancer effector cells." (PMID 39758935, 2025). "The following section discusses preclinical findings on the most promising bioengineer approaches that have been developed to maximize the anticancer therapeutic potential of IL-10 by improving its tumor specificity and increasing its intratumoral concentrations." (PMID 40149345, 2025). "The administration of arjunolic acid in this study led to a significant reduction in pro‐inflammatory cytokines such as TNF‐α, IFN‐γ, and IL‐6, along with lower levels of VEGF (a key factor in tumor angiogenesis) and a marked increase in anti‐inflammatory cytokine IL‐10." (PMID 40908716, 2025). "Evidence indicates that IL-10 can help tumor cells escape immune surveillance." (PMID 40469178, 2025). "In addition, IL-10 and IL-17A, among the top activated pathways, have been shown to have tumor-promoting roles." (PMID 39805854, 2025). "In solid tumors, T cells face formidable barriers imposed by the immunosuppressive tumor microenvironment (TME), including loss of MHC expression, recruitment of tolerogenic APCs, secretion of inhibitory cytokines (e.g., TGF-β, IL-10), and upregulation of immune checkpoint ligands such as PD-L1." (PMID 41374974, 2025). "Tumor-supportive neutrophils suppress both innate and adaptive immunity through various mechanisms, including the secretion of ROS, and immunosuppressive cytokines such as IL-10 and TGF-β, and contact-dependent suppression via PD-L1." (PMID 40050933, 2025). "IL-12 and TNF-α, secreted by M1-type macrophages, are typical pro-inflammatory factors that activate and recruit additional immune cells to participate in tumor killing, while IL-10, secreted by M2-type macrophages, inhibits the inflammatory response and attenuates immune function." (PMID 41383334, 2025). "In CC, TAM tumor infiltration produces IL-10, which promotes metastasis." (PMID 39941714, 2025). "It is hypothesized that LRFN4 promotes the conversion of TAMs into immunosuppressive M2 - type macrophages, which secrete cytokines such as interleukin-10 and transforming growth factor-β that inhibit anti-tumor immune responses." (PMID 40386777, 2025). "IL-10's ability to suppress macrophage function may facilitate tumor evasion during immune detection, contributing to the advancement of LC." (PMID 41179937, 2025). "Similarly, IL-10 displays both pro- and anti-tumor properties, depending on the cellular and molecular context." (PMID 41155372, 2025).
tumor (continued). "Regulatory immune cells, including Tregs, myeloid-derived suppressor cells (MDSCs), and M2-polarized tumor-associated macrophages (TAMs), further shape this suppressive ecosystem by producing inhibitory cytokines (e.g., TGF-β, IL-10) and depleting key metabolic substrates required for TIL fitness." (PMID 40475782, 2025). "It is well recognized that IL-10 has dual roles as anti-tumor and pro-tumor." (PMID 40933989, 2025). "Notably, TAMs from larger tumors exhibited increased IL-10 production, suggesting that either larger tumors enhance M2 polarization or M2 macrophages accelerate tumor growth." (PMID 40136652, 2025). "IgG4+B cell presence correlates with IL-10 tumor expression." (PMID 40933989, 2025). "In addition to creating physical barrier that restricts immune cell infiltration, components of the TME and tumor cells secrete various immunosuppressive molecules, such as IL-10, TGF-β, and vascular endothelial growth factor (VEGF)." (PMID 40420798, 2025). "Conversely, TAMs may promote tumourigenesis by supporting tumour invasion, angiogenesis, or the expression of immunosuppressive molecules, including IL-10, TGFβ, and immune checkpoint ligands such as PD-L1, which inhibit cytotoxic T-cell immunosurveillance." (PMID 40523200, 2025). "However, the role of IL-10 in angiogenesis is discussed controversially, attributing both pro- and anti-angiogenic characteristics, especially in the context of tumour angiogenesis." (PMID 39940657, 2025). "Conversely, in the tumor-promoting microenvironment, keratinocytes may be induced to secrete immunosuppressive factors like IL-10, which can inhibit NK and T cell function." (PMID 41346595, 2025). "In addition to IL-6, CAFs can produce many other interleukins, including IL-10, IL-11, IL-22, IL-32, and inhibiting actions of these interleukins resulted in anti-tumour effects in some studies." (PMID 39780187, 2025). "TAMs can polarize into multiple subtypes, influenced by factors such as colony‐stimulating factor 1 (CSF‐1) and chemokine (C‐C motif) ligand 2 (CCL2), and often express M2‐like markers including CD206, CD163, Arginase 1 (ARG1), and IL‐10, all of which promote tumor progression." (PMID 40553053, 2025). "Similarly, the experimental groups also produced more IL-10, with the DCV2 + T + Tumor group secreting significantly less IL-10 compared to the DCV1 + T + Tumor group." (PMID 40573908, 2025). "IL-10 is an immunosuppressive cytokine, meaning it helps the immune system tolerate the tumor environment, which could influence how well treatments work." (PMID 40647640, 2025). "In addition, IL-10 was expressed in the tumor stromal cells and epithelial cells of both premalignant and malignant CR lesions." (PMID 40149674, 2025). "In patients affected by BCC, a more indolent and less aggressive form of skin cancer, tumor-infiltrating lymphocytes (TILs) express both type 1, i.e., IL-2 and IFNγ, and type 2, i.e., IL-4 and IL-10 cytokines, with the former mainly produced by TILs and the latter by adherent, TIL-depleted cells." (PMID 40868818, 2025). "Previous studies have demonstrated that the inhibition of the PI3K/AKT/mTOR pathway can reduce the numbers of MDSCs and Tregs and decrease their secretion of immunosuppressive factors, such as TGF-β and IL-10, thereby improving immune activity within the tumor microenvironment." (PMID 39972480, 2025). "Manipulating the functionality of DC-SIGN+ cells to decrease IL-10 production could enhance anti-tumor immunity." (PMID 40076949, 2025). "IL-10 also reduces the expression of MHC-I on tumor cells, resulting in tumor immune escape." (PMID 41041322, 2025). "Second, the metabolic reprogramming of macrophages in proximity to apoptotic tumor cells may further reinforce an immunosuppressive microenvironment, characterized by elevated IL-10 and PGE2 secretion." (PMID 41201629, 2025).
tumor (continued). "Furthermore, this study demonstrated that oral administration of the CB‐AKK combined bacteria significantly increased the levels of TNF‐α in both tumor tissues and serum, whereas simultaneously reducing the levels of IL‐6 and IL‐10." (PMID 40497373, 2025). "It is possible that the tumor-derived interleukin IL-10 to facilitate the aberrant DC maturation." (PMID 40055269, 2025). "In addition, IL-10+ B1a cells selectively accumulate in melanoma and promote tumor growth by inhibiting tumor-infiltrating CD8+ T cells." (PMID 39744696, 2025). "Although IL-10 is generally considered protective, in the context of cancer it may also contribute to the establishment of an immunosuppressive tumor microenvironment, highlighting its dual role during CRC progression." (PMID 41614846, 2025). "While Tregs in the tumor microenvironment could suppress immune response by secreting cytokines such as IL-10 and TGF-β, thereby protecting tumor cells from attack." (PMID 39744497, 2025). "Meanwhile, IL-10 helps sustain T-cell function and can maintain immune activation without inducing excessive inflammation, supporting a more prolonged and controlled anti-tumor immune response." (PMID 40124384, 2025). "IL-10 has a bidirectional regulatory effect on tumor immunity." (PMID 39980556, 2025). "It is important to recognize that IL-10 has complex roles in the tumor microenvironment." (PMID 39931062, 2025). "The blockade of PD-1, combined with IL-10 neutralization, augmented the anti-tumor response." (PMID 40244064, 2025). "Tumor-derived IL-10 impairs DC vaccine efficacy, and blockade of IL-10 production or anti-IL-10R antibody administration synergizes with DC vaccines to suppress tumor growth in tumor-bearing models." (PMID 41430039, 2025). "IL-10 production by tumor-infiltrating macrophages was impaired by S3QEL 1.2." (PMID 39841829, 2025). "We were interested to know if the observed reduced tumor burden by LNS8801 may be mediated through one or both IL‐10 and IFN‐γ." (PMID 39282758, 2025). "In malignant ascites, CAFs express certain genes related to the immune system, such as complement factors, chemokines (e.g., CXCL1/2/10/12), and cytokines (e.g., IL6, IL10), which subsequently enhance tumor formation, invasion, and progression through the activation cadherins and integrins." (PMID 40075635, 2025). "In addition, interleukin IL-10 signaling system-mediated biological responses also include immunosuppression, enhanced anti-bacterial and antiviral capabilities, increased anti-tumor activity, and promotion of self-tolerance in autoimmune disorders." (PMID 41300695, 2025). "Growing validations indicated that the KRAS mutations may mainly produce an immunosuppressive TME by facilitating the development of immunomodulatory markers in tumor cells, including interleukin-6, transforming growth factor, and interleukin-10." (PMID 40075634, 2025). "In addition, TGF-β and IL-10 secreted by tumor cells and TAM inhibit DC-mediated antigen presentation and adaptive immune responses." (PMID 41246345, 2025). "Conversely, alternatively activated (M2) macrophages are educated by tumor cells to develop an immunosuppressive phenotype, facilitating tumor growth through the release of anti‐inflammatory factors (IL‐10 and TGF‐β) or direct suppression of CD8+ T‐cell cytotoxicity." (PMID 41306557, 2025). "Only IL-10 was significantly and similarly elevated in all treatment groups which is probably tumor-mediated since a tumor-free mouse was used as naïve control and IL-10 plays a role in immunosuppression in the tumor microenvironment." (PMID 39789356, 2025). "Additionally, TAMs secrete chemokines, such as CCL2, CCL5, and IL-10, which recruit and induce other immunosuppressive cells, including regulatory T cells (Tregs) 24, 25, thereby further suppressing anti-tumor immune responses." (PMID 40303328, 2025).
tumor (continued). "Additionally, IL-23-secreting DCs promote Th17 cell infiltration into the tumor mass, while IL-10 from Th2 cells contributes to DC reprogramming within the tumor microenvironment." (PMID 40136652, 2025). "Moreover, imDCs also promote tumor progression by overexpressing Il-10, which suppresses T cell proliferation." (PMID 40730800, 2025). "Regarding the function of IL-10 in a cancer context, this interleukin may contribute to tumor progression by interrupting inflammation, leading to antitumor immunity." (PMID 40725135, 2025). "For example, IL-10 has been reported to have anti-angiogenic properties, which may help inhibit tumour growth." (PMID 39325360, 2025). "Enhanced expression of tumor-associated adhesion molecules promotes MDSC recruitment, subsequently reinforcing the immunosuppressive microenvironment via the secretion of NO, TGF-β, and IL-10." (PMID 40948940, 2025). "There is some experimental evidence highlighting the potential of HT to impede tumor progression by modulating the expression levels of IFN-γ, PD-1, IL-17A, and MHC I. Notably, IL-2, IL-10, and IL-17A have been implicated in inhibiting immune escape mechanisms." (PMID 40313970, 2025). "Additionally, emerging bioengineering strategies aim to enhance IL-10’s therapeutic potential by improving its stability, half-life, pharmacokinetics, and targeted-delivery and specificity to tumor sites, showing promising results in the preclinical studies." (PMID 40149345, 2025). "IL-10, secreted mainly by TAMs, supports immunosuppression by inhibiting the proliferation and activity of cytotoxic T lymphocytes while promoting the development of the M2 macrophage phenotype, which is associated with angiogenesis, EMT, and tumor growth." (PMID 40362280, 2025). "Additionally, TCM can inhibit the production of immunosuppressive factors like TGF-β and IL-10, which are prominent in the tumor microenvironment." (PMID 40406101, 2025). "In fact, in the tumor microenvironment, the higher the blast percentage, the more inflammatory factors released by tumor cells, such as IL-10, TGF (tumor growth factor), and further promote the recruitment of chemokines and build a platform for inflammatory storms." (PMID 40686821, 2025). "Additionally, they generate anti-inflammatory responses by secreting cytokines such as IL-10, participate in the generation of tumor blood vessels and remodel the extracellular matrix." (PMID 40463876, 2025). "Cytokines in tumor microenvironment such as tumor necrosis factor-α, interleukin (IL)-6, IL-10 and transforming growth factor-β may enhance this process, promoting tumor cell proliferation and survival, thereby affecting tumor spread to hematological system." (PMID 41221526, 2025). "Elevated IL-6 levels were strongly associated with advanced stages of HCC, reflecting heightened inflammation and liver damage, while higher IL-10 levels were observed in early tumor stages, indicating a role in early carcinogenesis and tumor-induced immunosuppression." (PMID 41379186, 2025). "When co-cultured with THP-1 macrophages, OCSLCs increase the expression of M2 markers such as CD163, while boosting the secretion of anti-inflammatory cytokines like IL-10 and pro-tumor factors such as VEGF and MMP-9, which are characteristic of M2 macrophages." (PMID 40330466, 2025). "B cell specific knockout of Sting, Il-10, or Il-35 reduced tumor growth." (PMID 40356924, 2025). "Phytic acid reduces the expression of pro-inflammatory markers such as cyclooxygenase 2 (COX-2), inducible nitric oxide synthase (iNOS), interleukin-1 beta (IL-1β), interleukin-6 (IL-6), and interleukin-10 (IL-10), creating a less favorable environment for tumor growth." (PMID 39942108, 2025).